CD1C (CD1c molecule)
Diseases named in the same sentence as CD1C in open-access papers (continued):
Sharing a sentence is not in itself a finding about the gene and the disease.
cancer (41 papers, 2014 to 2025). A tumor composed of atypical neoplastic, often pleomorphic cells that invade other tissues. "In our study, higher numbers of CD1c+ DCs located in close proximity to cancer islets were associated with greater diameter of metastasis as well as with HR-positive and HER2 overexpression." (PMID 35955602, 2022). "B cell_1, B cell_2, and cancer cell_3 were positively associated with prognosis, whereas low enrichment of CD1C+_B dendritic cell_3 had more favorable prognosis." (PMID 35769782, 2022). "Importantly, we discovered that four cell types (B cell_1, B cell_2, cancer cell_3, and CD1C+_B dendritic cell_3) were significantly associated with prognosis." (PMID 35769782, 2022). "Multiple studies describing CD1c+CD14+ DCs in cancer and healthy state reported similar phenotypes, characterized by co-expression of these monocyte/macrophage markers with cDC2 markers." (PMID 38242119, 2024). "Another observation was that cancers with the least DC CD1c+ present in the stroma (DC group 2) infiltrated surrounding tissues to a greater degree than ones most heavily infiltrated by CD1c+ cells (DCs group 4)." (PMID 36768258, 2023). "Cancers with the least DC CD1c+ or DC CD123+ had higher pT scores than ones that were more heavily infiltrated." (PMID 36768258, 2023). "As B cell_1 (C4), B cell_2 (C10), cancer cell_3 (C18), and CD1C+_B dendritic cell_3 (C16) were identified to be significantly associated with prognosis, we therefore analyzed their interactions among them and with other subgroups based on CellPhoneDB." (PMID 35769782, 2022). "With respect to HR status, we found higher densities of CD1c+ cells in the distant node area in HR-positive cancers than in HR-negative (51.01 ± 35.72 vs. 24.47 ± 28.73, p < 0.025)." (PMID 35955602, 2022). "Cancer cell_3 (C18) strongly interacted with CD1C+_B dendritic cell_1 (C6) and CD1C+_B dendritic cell_3 (C16)." (PMID 35769782, 2022). "CD1C+_B dendritic cell_3 played a key role in tumorigenesis and cancer progression possibly through CD74-MIF." (PMID 35769782, 2022). "DCs, especially CD1C+_B dendritic cell_3, played a critical role in cancer progression probably through CD74 signaling." (PMID 35769782, 2022). "In cancer patients CD1c+ cells were shown to represent DCs that are able to stimulate cytotoxic CD8+ and CD4+ helper T cells." (PMID 35955602, 2022). "This study supports the combined usage of CD1c+ mDCs and pDCs as a cellular anti-cancer immunotherapy, combining the beneficial effects of both subsets into one potent treatment modality." (PMID 30019146, 2018). "“PGE2 pathways in cancer” pathway was observed for the higher expressed profile of CD1c+ mDCs and the DN DC population." (PMID 29795118, 2018). "Both pDCs and CD1c+ mDCs have been tested clinically in cancer patients and antigen-specific T-cell responses and prolonged overall survival have been achieved." (PMID 30019146, 2018). "The first clinical studies utilizing primary blood DCs have recently been conducted by our group, demonstrating the safety and efficacy of CD1c+ mDCs and pDCs in cancer immunotherapy." (PMID 27057096, 2016). "Collectively, these studies emphasize a role for CD1c+CD14+ cells in cancer." (PMID 38242119, 2024). "Patients with the highest intrastromal DC CD1c+ density had the most cancers with low pT scores." (PMID 36768258, 2023). "Thus, pDCs, as well as CD1c+ mDCs, represent a promising target in DCs-based vaccine immunotherapy for cancer." (PMID 26959879, 2016). "Importantly, protamine–RNA complexes induced release of the Th1-skewing cytokine IL-12p70 from CD1c+ DCs, making the stimulus highly interesting when an anti-cancer response is desired." (PMID 26275446, 2015). "Most of the non-cancer cells are immune cells, with two distinct clusters of T lymphocytes, B lymphocytes, CD1C-CD141-dendritic cells+ and CD1C+_B dendritic cells." (PMID 39310253, 2024).
cancer (continued). "The DC_CD1C cells expressed CX3CR1, and the CX3CL1-CX3CR1 interaction was significantly enriched between DC_CD1C cells and cancer cells from MPR patients." (PMID 36869384, 2023). "We identified cDC2s (CD1C+FCER1A+) as the predominant cDC subset, paralleling with previous pan-cancer single-cell data." (PMID 36198671, 2022). "With this comparative study, we have reinforced the establishment of human circulating CD1c+ mDCs, CD141+ mDCs, and pDCs as promising candidates for DC-based immunotherapy in the context of cancer." (PMID 27057096, 2016). "Our analysis also identified several antigen-presenting molecules as potential cancer drivers, including one class I (HLA-C), one class II (HLA-DRB1), and three HLA-like proteins (CD1C, CD1E and MR1)." (PMID 26485003, 2015). "Independent of the cancer cell line used, monocytes failed to upregulate CD1c and only showed a small increase in CD14 expression in response to cancer cell line-derived cues." (PMID 38242119, 2024). "Comparison to patient tissue sections, stained with CD1c—indicating DCs with a myeloid origin—and PanCK, suggested that our co-cultures achieve representative interactions between cancer cells and DCs, even in the absence of other stromal cells." (PMID 36761758, 2023). "Notably, human CD1c (BDCA-1)+ myDCs are heterogeneous, with a CD14-positive subpopulation that is immunosuppressive and a CD14-negative subpopulation that is capable of mediating antitumor immune responses induced by immunogenic cancer cell death." (PMID 33182610, 2020).
adenocarcinoma (2 papers, 2016 to 2023). A common cancer characterized by the presence of malignant glandular cells. "Only DC CD1a+ and CD1c+ infiltrated adenocarcinomas’ glandular epithelium, the former in higher numbers (Me: 75; IQ: 41–119)." (PMID 36768258, 2023).
hematological cancers (1 paper, 2025). "This makes CD1c an ideal target for hematological cancers, as its restricted expression would limit toxicity in other healthy tissues." (PMID 40777002, 2025). "These proof-of-concept findings demonstrate that CD1c-targetting T cell engagers could be developed as novel therapeutics for hematological cancers, bypassing the limitations of HLA restriction." (PMID 40777002, 2025).
CD1C also shares sentences with these, for which no sentence is quoted: infectious disease (3 papers); allergies (2); atopic dermatitis (2); B-cell chronic lymphocytic leukemia (2); bacterial infection (2); colorectal cancer (2); glioblastoma (2); hematological malignancies (2); hypersensitivity pneumonitis (2); inflammatory bowel disease (2); Langerhans cell histiocytosis (2); liver cancer (2); acute monocytic leukemia (1); Airway obstruction (1); allergic rhinitis (1); Angina (1); ankylosing spondylitis (1); arthropathy (1); bacteremia (1); Blindness (1); bronchiectasis (1); cardiac disease (1); cerebral infarction (1); cervical cancer (1); chronic heart failure (1); clear cell renal cell carcinoma (1); diabetes (1); dyslipidemia (1); E. coli infection (1); falciparum malaria (1).
A further 39 diseases each share a sentence with CD1C in 1 paper.